C1orf159 (chromosome 1 open reading frame 159)
Synonyms: FLJ20584
Tractability: Antibody: UniProt predicts a signal peptide or a membrane-spanning region.
Gene: Protein-coding gene on chromosome 1 (1,081,811 to 1,116,361, reverse strand). Ensembl gene ENSG00000131591.
Subcellular location: Membrane
Subcellular location (Human Protein Atlas): Mitotic chromosome; Nucleoli rim; Intermediate filaments
Gene Ontology:
Cellular component: membrane
Genetic constraint (gnomAD): Loss-of-function variants: 19 observed, 24.71 expected, observed/expected ratio (o/e) 0.77, 90% interval 0.54 to 1.13. The upper end of that interval is the gene's LOEUF score, 1.13, which puts it in group 4 of 6, group 1 being the genes least tolerant of losing a copy. Missense variants: 274 observed, 284.34 expected, observed/expected ratio (o/e) 0.96, 90% interval 0.87 to 1.07. Synonymous variants: 139 observed, 123.41 expected, observed/expected ratio (o/e) 1.13, 90% interval 0.98 to 1.3.
Homologues: Orthologues: macaque C1H1orf159 (83% identical), guinea pig C1orf159 (78% identical), rat C5h1orf159 (73% identical), mouse 9430015G10Rik (72% identical), chimpanzee C1H1orf159 (70% identical), dog C5H1orf159 (64% identical), tropical clawed frog c7h1orf159 (47% identical), zebrafish si:ch211-157b11.12 (40% identical).
Diseases named in the same sentence as C1orf159 in open-access papers:
C1orf159 is named in the same sentence as 3 diseases in open-access papers, as found by Europe PMC text mining. Sharing a sentence is not in itself a finding about the gene and the disease. The quoted sentences say what the papers report.
cancer (1 paper, 2024). A tumor composed of atypical neoplastic, often pleomorphic cells that invade other tissues. "C1orf159 is a protein coding gene whose increased expression was found to be an unfavourable prognostic marker in renal and liver cancer." (PMID 38198623, 2024).
infection (1 paper, 2017). The state of being infected such as from the introduction of a foreign agent such as serum, vaccine, antigenic substance or organism. "C1ORF159 and IER2 levels change comparably upon infection in wild-type HeLa and BBC3as knockout cells, as measured by RT-qPCR and Nanostring nCounter assays." (PMID 29089033, 2017).
C1orf159 also shares sentences with these, for which no sentence is quoted: triple-negative breast carcinoma (1 paper).